LINC02145 (long independently transcribed non-coding RNA 2145)
Synonyms: CTC; FLJ33360
Gene: Long non-coding RNA gene on chromosome 5 (6,310,441 to 6,339,884, reverse strand). Ensembl gene ENSG00000250490.
Diseases named in the same sentence as LINC02145 in open-access papers:
LINC02145 is named in the same sentence as 3 diseases in open-access papers, as found by Europe PMC text mining. Sharing a sentence is not in itself a finding about the gene and the disease. The quoted sentences say what the papers report.
asthma (2 papers, 2020 to 2022). "Subsequent network analysis based on PCC figured out several key lncRNAs probably interacted to those key asthma-related genes, i.e., LINC02145, GUSBP2." (PMID 32948203, 2020).
LINC02145 also shares sentences with these, for which no sentence is quoted: Cerebellar hypoplasia (1 paper); hypospadias (1).